CD28 (CD28 molecule)
Diseases named in the same sentence as CD28 in open-access papers (continued):
Sharing a sentence is not in itself a finding about the gene and the disease.
tumor (continued). "We chose CD28 reasoning that constitutive activation could amplify the deployment of effector functions at early stages of tumor infiltration and trigger chemo-attraction to expand the therapeutic window, while premature exhaustion could be countered by suppression of PD-1." (PMID 34743703, 2021). "Human tumor cells and tumor-associated APCs often express high levels of PD-L1, PD-L2, ICOS-L, and B7-H3, which causes high co-inhibitory signals that are accompanied by a low CD28 co-stimulation of T cells, which is itself caused by low to absent CD80 and/or CD86 signals." (PMID 34948104, 2021). "Similarly to the CTLA-4/CD28 dynamic, TIGIT outcompete DNAM-1 (CD226) and CD96 for the binding of CD155, impeding DNAM-1 positive co-stimulation and delivering a direct inhibitory signal as shown in TIGIT-deficient mice with delayed tumor growth." (PMID 34572799, 2021). "With these findings, we hypothesize that the CD28-CAR association may increase CAR sensitivity for ectopically expressed low abundant antigens, such as the CD19 expressed on mural cells, thus demonstrating higher off-tumor activation of CARs." (PMID 33833759, 2021). "Given that the expression of CD28 is markedly higher in primary tumor tissues than in healthy tissues, T lymphocyte activity might be inhibited in tumor tissue, which results in an immune-suppressed microenvironment that participates in endowing cells with oncogenic functions." (PMID 32967633, 2020). "PD-L1, belonging to the CD28+ cytotoxic T-lymphocyte associated protein 4 (CTLA-4) receptor subfamily, is an extremely important costimulatory molecule in immune response, and it displays a leading role in inducing immune tolerance in the microenvironment of the tumor." (PMID 32884946, 2020). "The CD28 costimulatory pathway, an essential pathway that can signal for the activation of naïve T cells and might participate in cancer immunity, is also required for tumor clearance." (PMID 32967633, 2020). "However, other evidence demonstrates that the tonic activation of CAR T-cells with the CD28 endo-domains is responsible for the suboptimal anti-tumor activity observed in vivo as the T cells exhaust rapidly, resulting into a decrease in cell proliferation and cytokine production." (PMID 33374128, 2020). "Consistent with previously-reported transcriptomic analyses of tumours following treatment with IgE in vivo, we found heightened classical immune activation signalling pathways (e.g., FcγR signalling and functions, and CD28 co-stimulation signalling) following IgE cross-linking." (PMID 33203088, 2020). "Moreover, in an orthotopic mouse model of MPM, migration toward the tumor was circumvented by intra-pleural administration of second generation, CD28-costimulated MSLN CAR T-cells and led to a larger reduction of pleural an metastatic tumor load as compared to intravenous administration." (PMID 32582537, 2020). "We have previously shown in MM that CD28 activation by itself transduces a major pro-survival/chemotherapy resistance signal, and others have shown that CD28 signaling in MM can decrease MM cell susceptibility to CD8 T cell-mediated anti-tumor immune responses." (PMID 32751699, 2020). "However, CD28 expression in CD8+ T cells may be down-regulated in patients with tumors because of tumor antigens’ chronic stimulation." (PMID 31623615, 2019). "Hence, we speculated that CD28 expression in CD8+T cells influences their anti-tumor immune response in NSCLC patients, and, consequently, impact patients’ survival." (PMID 31623615, 2019). "Since CD28 co-signalling is essential to activate naive T cells and to induce Teff responses, EBV+ SMT in the context of CARMIL2-deficiency might evade anti-tumour immunity and indicate a particular importance of CD28 co-signalling in controlling this tumour entity." (PMID 28112205, 2017).
tumor (continued). "In addition, there is evidence that the incorporation of CD28 co-stimulatory domain into CARs may avoid some of the mechanisms that tumor cells utilize to escape from T cells." (PMID 28496440, 2017). "As we have shown, the bi-specific aptamer is enriched in tumors with higher concentration of MRP1, which indicates that the bi-specific MRP1-CD28 aptamer could be used to elicit targeting tumor immunity in a much more efficient fashion than the CD28 agonist aptamers." (PMID 26992239, 2016). "Additionally, there was no apparent association between CD28 expression on tumor cells or TILs and clinical outcomes." (PMID 26918337, 2016). "Based on the premise that lack of costimulation at the tumor site might hamper the ability of tumor-specific T cells to eliminate the tumor cells, we developed a bi-specific aptamer that is aimed at targeting CD28 costimulation to chemotherapy-resistant MRP1 cancer cells." (PMID 26992239, 2016). "However, as the stimulus induced by CD28 tumor-targeting promotes Th1 cytokines (IFN-γ, TNF-α) but it also promotes the immunosuppressive cytokines (IL-10), we reasoned that, in order to have an antitumor effect, the immunosuppressive environment should be diminished." (PMID 26992239, 2016). "However, we speculated that pre-activation of T cells by interleukin 2 (IL-2) in combination with anti-CD3/anti-CD28-coated beads and subsequent co-receptor-mediated cross-linkage to tumor cells could perhaps already be operative." (PMID 24751697, 2014). "In addition to CD4+ Tregs also CD8+CD28- Tregs could be isolated from peripheral blood, tumor tissue and metastatic lymph nodes of CRC patients." (PMID 24212779, 2011). "Based on results obtained with CAR-T (CD3z-CD28) cells, the regimen used for CAR-T (3Z-41BB) cells was modified: dosing at 0.02 million cells per egg, i.e., an effector-to-tumor ratio (E:T) of 0.2:1, either once at EDD11, or twice at EDD11 and EDD14." (PMID 41596451, 2026). "High tumor burden; early/severe CRS; CD28‐based constructs; older age; preexisting neurological disease or CNS involvement." (PMID 41207679, 2026). "CD28-based CAR-T cells induced faster and more pronounced tumor regression, while 4-1BB-based CAR-T cells showed weaker activation, resulting in reduced differentiation and exhaustion." (PMID 41153826, 2025). "We utilized flow cytometry to evaluate the expression of CD28 on CD8+ T cells in 120 peripheral blood samples and 81 tumor tissue samples." (PMID 40136325, 2025). "Especially, a positive correlation between ACAA1 expression in tumor cells and six immune checkpoint-related genes, namely CD27, PDCD1, CD86, BTLA, TIGIT, and CD28, on immune cells within the tumor microenvironment." (PMID 41277949, 2025). "Regarding PBMC-mediated lysis of tumor cells, the subsequent cytotoxicity assays showed that the blockade of CD39 led to an increased CD3/CD28 stimulated PBMC-mediated lysis of MM cells." (PMID 40274631, 2025). "It was demonstrated that CAR CD28-engineered T cells exhibited enhanced glycolytic capacity and metabolic fitness compared to CAR 41BB-engineered T cells, resulting in superior anti-tumor efficacy." (PMID 40181966, 2025). "To assess the specificity and cytotoxic potential of our NKG2D/CD28&CAR-T cells, we analyzed the expression of target antigens and NKG2DLs across a panel of tumor cell lines." (PMID 40181405, 2025). "The main areas of development concern trispecific antibodies that, by adding to the binding with the tumor antigen, introduce recruitment of effector cells, such as T cells via CD3, and co-stimulatory signal activation, for example, CD38 and CD28." (PMID 40003906, 2025). "To investigate the association between high expression of CD40 and the T-cell costimulatory molecules CD28 or GITR in an "immunologically hot" tumor microenvironment, we performed a univariable analysis stratified by the tumor's CD4/CD8 expression status." (PMID 41182434, 2025).
tumor (continued). "Chronic antigen stimulation found in cancer, leads to the accumulation of CD28- CD8+ T cells, further promoting tumor progression." (PMID 39744475, 2025). "Candidates possibly involved in modulating T cell activity include CD28/CD80, ICOS/ICOSL, OX-40/OX-40L, and B7-H6/NKp30, but very little is known as to their role in tumor–immune communication." (PMID 40649953, 2025). "Still, we plan to evaluate Siglec-7 CSRs incorporating CD28 and OX40, with the aim of further optimizing this approach for distinct tumor microenvironments in future studies." (PMID 40433387, 2025). "Therapeutically, anti-CTLA-4 monoclonal antibodies, such as ipilimumab and tremelimumab, enhance anti-tumor immunity by blocking inhibitory CTLA-4 signals, and thereby restore T-cell effector function and increase CD28-mediated costimulation." (PMID 40723175, 2025). "To evaluate the in vivo antitumor efficacy of NKG2D/CD28&CAR-T cells, we established mouse tumor models using fluorescently-labeled cell lines for both solid and hematological tumors." (PMID 40181405, 2025). "Previous studies consistently reported that the expressions of LAG-3, PD-1, PD-L1, CD28, CD80, CD27 and CTLA-4 were relevant to the immunosuppression in the tumor microenvironment." (PMID 39781354, 2025). "Conversely, adoptive transfer of CD19.4–1BB CAR-T cells was associated with a significantly greater frequency of initial tumor growth, but of note, there were fewer relapses as compared to mice treated with CD19.CD28 CAR-T cells." (PMID 40568128, 2025). "For the immune part, we focused on the TCR-mediated signaling pathway and major immune checkpoints including PD-1, PD-L1, CD28, CD80/CD86, LAG3, CTLA4, TIGIT, CD155, OX40, OX40L, 4-1BB, and 4-1BBL (expressed on T cells, tumor cells, or APCs)." (PMID 40276607, 2025). "Resting T-cells that had been activated with anti-CD3 and anti-CD28 antibodies and cultured with SCC-154 spheroids showed suppressed proliferation, indicating tumor driven immunosuppressive effects of these spheroids." (PMID 40176808, 2025). "In contrast, NKG2D/CD28& MSLN CAR-T cells maintained robust antitumor activity in this low-density antigen context, leading to complete tumor clearance in all mice." (PMID 40181405, 2025). "CD28 is a common stimulus molecule for CD8, providing the activation signal that prompts CD8 (+) T cell activation to exert anti-tumor effects." (PMID 40356964, 2025). "Its interaction with ligands PD-L1 (CD274) and PD-L2, expressed on tumor cells and immune cells within the tumor microenvironment (TME), attenuates T-cell receptor (TCR) signaling and co-stimulatory pathways (e.g., CD28), promoting immune escape." (PMID 40649207, 2025). "In the model, T cell activation occurs through the binding of TCR/CD3 complex to major histocompatibility complex (MHC) on APCs and tumor cells, accompanied by the physical interaction between CD80/CD86 on APCs and CD28 on T cells." (PMID 40276607, 2025). "Cytotoxicity assays demonstrated that overexpressing CD2 increased the ability of different CAR-T cells, which employ either 4-1BB or CD28 as the costimulatory domain, to eliminate CD19-low-expressing tumor cells." (PMID 40615696, 2025). "The high expression of NKG2DL provides an additional target for NKG2D/CD28&CAR-T cells, enhancing their cytotoxic potential against tumor cells with varying antigen densities." (PMID 40181405, 2025). "To investigate the effects of CD28 and PD1 expression on CD8+ T cell functionality, we analyzed tumor-infiltrating T cells extracted from 11 EC patients, focusing on their cytokine expression profiles." (PMID 40136325, 2025). "Nearly twice as many CD28-costimulated L1CAM-CAR T cells infiltrated (mean=196,839 T cells, range=190,276-201,389 cells) the tumor model compared to 4-1BB costimulated L1CAM-CAR T cells (mean=104,381 T cells, range: 87,304-129,403)." (PMID 41394860, 2025).
tumor (continued). "Costimulatory molecules, such as CD28, 4-1BB, and ICOS, are essential for activating tumor-specific T cells, leading to their proliferation and activation for effective tumor clearance." (PMID 40260303, 2025). "Immune checkpoint blockade therapies, which target immune cells expressing CTLA4,CD28,ICOS and PD1 in the tumor microenvironment, represents a first-generation antibody-based therapy for cancer." (PMID 40027134, 2025). "IL-2, a key growth factor for tumor-infiltrating lymphocytes, suggests that CD8+CD28+PD1− T cells possess superior proliferative potential." (PMID 40136325, 2025). "CD19.CD28 CAR-T cells initially were more effective at killing the tumor and preventing initial tumor growth." (PMID 40568128, 2025). "CD28 facilitates LCK-mediated phosphorylation of the CD3ζ chain, promoting immediate T-cell activation and rapid tumor-killing by CAR T-cells." (PMID 40298832, 2025). "Preclinical studies, including triple-specific TCEs targeting CD3, CD28, and CD38, have shown superior tumor-killing potency and sustained immune responses in complex cancers such as multiple myeloma." (PMID 39982231, 2025). "The migration of Tregs to the tumor site is also dependent on the glucose fermentation process, and the activation of PICOP by the surface molecule CD28 is stimulated." (PMID 40696413, 2025). "utilized CRT mRNA in combination with EVs containing anti‐CD3/CD28 fragments, which interacted with CD3/CD28/TCR on the surface of T cells to activate T cells to accomplish CRT high expression in T cells and obtain a better effect on killing tumor cells." (PMID 41476648, 2025). "REGN7075 is a first-in-class EGFR x CD28 BsAb that activates T cell response by bridging CD28-expressing T cells and EGFR-expressing tumor cells." (PMID 40565299, 2025). "Briefly, TILs were grown from the tumor fragments in high-dose IL-2 conditions and stimulated with anti-CD3/CD28 microbeads at day 0 as shown in." (PMID 40145091, 2025). "This corroborates our previous findings showing that HER2-TAC T cells outperformed CD28-based HER2-CAR T cells in a solid tumor mouse model with increased antitumor efficacy, reduced toxicity, and faster tumor infiltration." (PMID 39404622, 2025). "Within the tumor microenvironment (TME), CD86 binds to CD28 and CTLA-4 on the surface of T cells, regulating T cell activation, proliferation, and survival." (PMID 41006647, 2025). "In both the A549 and H1299-MSLNLow tumor models, MSLN CAR-T cells and NKG2D/CD28&MSLN CAR-T cells demonstrated significant tumor regression compared to the non-transduced T cell control group, as evidenced by reduced tumor volumes and in vivo imaging." (PMID 40181405, 2025). "During tumor elimination, the interaction of CD80 and CD86 on antigen-presenting cells with CD28 on T cells regulates T-cell activation, thereby initiating T-cell proliferation." (PMID 40343258, 2025). "While these observations suggest potential advantages of NKG2D/CD28&CAR-T cells, further studies are required to evaluate their impact on CAR-T cell persistence and tumor clearance in therapeutic settings." (PMID 40181405, 2025). "In both the Nalm6 and K562-CD19Low tumor models, the NKG2D/CD28&CD19 CAR-T cell group demonstrated prolonged survival and greater tumor growth inhibition compared to the traditional CD19 CAR-T cells." (PMID 40181405, 2025). "Incorporating one or two costimulatory domains, such as CD28, 4-1BB, CD27, OX40, and ICOS, into the CAR structure significantly enhanced T cell proliferation, persistence, and anti-tumor efficacy in vivo." (PMID 39633491, 2024). "Here, without lentivirus and professional antigen presenting cell application, a novel tumor-specific T-cell therapy was successfully developed only by co-culturing MHC+ cancer cells and Naïve-T cells under the CD28 co-stimulatory signals." (PMID 39158647, 2024).
tumor (continued). "More importantly, BACH2-mediated CD28 and CD40LG signals contributed to cell migration and dissemination of T-ALL cells to the bone marrow, thus adding a new layer to the BACH2-mediated tumor immunoregulation in T-cell malignancies." (PMID 38233409, 2024). "Tissue microarrays of the invasive front as well as the tumor core of BCC and cSCC samples were used to evaluate PD-1, PD-L1, CD28, and CD86 expression and their topographic distribution profiles by chromogenic immunohistochemistry." (PMID 39329753, 2024). "Recently, a trispecific antibody that interacts with CD38 on tumor cells and CD3 and CD28 on T cells displayed enhanced cytotoxicity to tumor cells." (PMID 38672132, 2024). "Blockade of CD28 or CD40LG, including but not limited to genetic or pharmacologic means, mAbs and chimeric antigen receptor-based therapy, will suppress tumor growth and BM infiltration, thereby offering a novel therapeutic approach for the treatment of T-ALL." (PMID 38233409, 2024). "Anti-CD3, anti-CD28 and IL-2 preactivated immune cells were co-cultured with LLC or SJT1601 tumor cells directly for 24 h or 48 h in vitro, and then suspended cells were collected for flow cytometry." (PMID 39004699, 2024). "Subsequently, they further modified the GD2.CD28.CD3ζ-CAR by attaching an anti-CD73 single-chain variable fragment (scFv) through a cleavable, tumor-sensitive linker, creating the CD73 scFv-GD2.CD28.CD3ζ-CAR." (PMID 38694508, 2024). "Numerous studies have highlighted the suppressive role of CD8 + CD28- T cells in regulating tumour immunity, suggesting that the presence of cell surface markers CD8+ and CD28- signifies a senescent or exhausted phenotype of T cell." (PMID 38519706, 2024). "With a higher affinity for the ligands CD80 and CD86 on antigen-presenting cells (APCs) than the co-stimulation receptor CD28 on T cells, the interaction between CTLA4 and its ligands suppresses T-cell activity, thereby promoting tumor growth." (PMID 39198311, 2024). "L1CAM short spacer-CD28/ζ CAR T cells expanded and induced initial tumor regression more than the long spacer at the tumor site in the face of the cancerous target." (PMID 38178096, 2024). "Recent research highlights the pivotal role of co-stimulatory molecules, including CD28 and CD137, in regulating T-cell metabolic pathways, offering promising targets for immunotherapy to boost T-cell anti-tumor activity." (PMID 38891056, 2024). "To further enhance anti-tumor efficacy of TAC-T cells in the treatment of solid tumors, here we report a novel NECTIN-4-redirected TAC containing the co-stimulatory CD28 cytoplasmic domain." (PMID 39735536, 2024). "Based on this, the second generation of CAR-T cells had one co-stimulatory domain CD28, 4-1BB, ICOS or OX40 in the intracellular domain, which were significantly enhanced in the activation, proliferation, cytokine secretion and anti-tumor ability." (PMID 39372412, 2024). "In this work, we generated a novel cellular model of TITRs by culturing peripheral blood mononuclear cell-derived regulatory T cells in medium containing tumor cell-conditioned medium, CD3/CD28 activator, interleukin-2 and 1α,25-dihydroxyvitamin D3." (PMID 38231448, 2024). "The system was used to evaluate the anti-tumour effect of ROR1CAR-T cells composed of a ROR-1-specific single-chain antibody, an IgG4-Fc-derived hinge, the CD28TM domain, and 4-1BB-CD3ζ or CD28-CD3ζ signaling modules." (PMID 38475858, 2024). "We demonstrated by GSEA that genes highly expressed in tumor-infiltrating Tregs in these studies were enriched in TNFR2-costimulated tTregs, while genes with low expression were enriched in CD28-costimulated tTregs." (PMID 38341270, 2024). "Our results highlight the facts that PD-1, PD-L1, and CD28 expression was significantly higher in cSCC as compared to BCC for both the invasive front and the tumor core." (PMID 39329753, 2024).